STAT3 (signal transducer and activator of transcription 3)
Diseases named in the same sentence as STAT3 in open-access papers (continued):
Sharing a sentence is not in itself a finding about the gene and the disease.
chronic lymphocytic leukemia (59 papers, 2010 to 2025). "STAT3 signaling in CAR T cell products has been associated with improved responses in chronic lymphocytic leukemia patients and modulation of STAT3 signaling has been used to improve CAR T cells in other preclinical models." (PMID 34177932, 2021). "A completed clinical trial of PYR as a STAT3 inhibitor in chronic lymphocytic leukemia reported in vivo efficacy of STAT3 suppression, overall safety, and stable disease for 50% of the patients (NCT01066663)." (PMID 40027760, 2025). "Increased IL-6 in sera of chronic lymphocytic leukemia (CLL) patients correlates with STAT3-dependent dampening of T cell proliferation and IL-2 production." (PMID 39281678, 2024). "The CXCL12/CXCR4/STAT3 pathway can promote the expression of IL-10 in chronic lymphocytic leukemia (CLL) cells, inducing immunosuppression." (PMID 38920657, 2024). "In chronic lymphocytic leukemia, IL-23-activated STAT3 contributes to the enhanced function of CAR-T cells." (PMID 36761742, 2023). "While the efficacy of IL-21-driven STAT3 signaling in T cell immunotherapy is still being explored, STAT3 signaling has been correlated with improved CD19 CAR T cell treatment outcomes in chronic lymphocytic leukemia." (PMID 34177932, 2021). "These authors also indicate that STAT3 phosphorylation on Ser727 in chronic lymphocytic leukemia (CLL) is more elaborate since it requires the assembly of a CK2/CD5/B-Cell Linker Protein (BLNK)/STAT3 complex." (PMID 29464030, 2018). "Ibrutinib, a Bruton's tyrosine kinase inhibitor, was shown to down-regulate PD-L1 expression on tumor cells and PD1 in CD4+ and CD8+ T cells via inhibition of STAT3 and also decreased IL-10 production by chronic lymphocytic leukemia (CLL) cells in patients." (PMID 30420856, 2018). "In chronic lymphocytic leukemia (CLL) STAT3 is constitutively phosphorylated exclusively at serine 727 and exhibits DNA-binding and transcription activating activity on known STAT3 target genes." (PMID 25568664, 2014). "Previous study reported that IL-10 could promote tumorigenesis or progression through STAT3 signaling in diverse diseases, like chronic lymphocytic leukemia and breast cancer." (PMID 37779872, 2023). "Moreover, a study from Uri Rozovski and colleagues also stated that STAT3 regulates miR-135b in chronic lymphocytic leukemia." (PMID 33990540, 2021). "For example, serine phosphorylation of STAT5 was required for BCR-ABL-induced leukemogenesis, and phosphorylation of S727 on STAT3 augmented the induction of genes involve in the cellular growth and survival that contributed to progression of chronic lymphocytic leukemia." (PMID 34809691, 2021). "The pro-apoptotic effect of cucurbitacin I was seen in B-leukaemia cells and primary chronic lymphocytic leukaemia, where the inhibition of phosphorylated STAT3 led to the downregulation of an anti-apoptotic gene, XIAP, and the cell cycle regulatory gene, CDC2 and upregulated DR4." (PMID 32731620, 2020). "The JAK2/STAT3 in particular has a key role in conveying signals that elicit the transcription of pro-survival and anti-apoptotic genes, such as Mcl-1 and Bcl-2, both known to be over-expressed in chronic lymphocytic leukemia (CLL)." (PMID 31817171, 2019). "Others have found that STAT3 activates NF-κB in chronic lymphocytic leukemia cells." (PMID 29029486, 2017). "Similarly, SMYD3 is directly regulated by STAT3 in chronic lymphocytic leukemia." (PMID 39482529, 2024). "Chronic lymphocytic leukemia (CLL) cells produce IL-10 via STAT3 signaling, which can suppress T cell effector function." (PMID 30420856, 2018). "Unlike the phosphorylation of STAT3, little is known about the acetylation of STAT3 in chronic lymphocytic leukemia (CLL) cells." (PMID 30263097, 2018).
chronic lymphocytic leukemia (continued). "In chronic lymphocytic leukemia (CLL), the CXCL12/CXCR4 axis induces immune suppression via Signal Transducer and Activator of Transcription 3 (STAT3) phosphorylation in B and T-CLL cells." (PMID 32260318, 2020). "In another study, curcumin was found to induce apoptosis in Chronic lymphocytic leukemia (CLL) B cells in a dose-dependent manner and inhibited constitutively active pro-survival pathways including STAT3, AKT, and NF-κB." (PMID 32143311, 2020). "STAT3 drives the expression of LPL, which catalyses the hydrolysis of triglycerides into free FAs in chronic lymphocytic leukaemia." (PMID 32731620, 2020). "Transcriptomic profiling from chronic lymphocytic leukemia patients successfully treated with CAR-T cells, revealed a general implementation of the IL-6/STAT3 signaling pathways, as indicated by increased production of IL-6, IL-17, IL-22, IL-31 and CCL20." (PMID 30999624, 2019). "For example, in chronic lymphocytic leukaemia (CLL) c-ABL has been shown to drive high MCL-1 mRNA and protein expression through STAT3/NF-κB." (PMID 29769323, 2018). "Chronic lymphocytic leukemia (CLL) cells possess regulatory functions comparable to those of normal B10 cells, a regulatory B cell subset that suppresses effector T-cell function through STAT3-mediated IL-10 production." (PMID 29379494, 2017). "Higher dose leflunomide has also been shown to inhibit the proliferation and survival of chronic lymphocytic leukemia (CLL) cells in vitro through “off-target” effects on signaling pathways such as NF-kappa B and STAT3." (PMID 28574826, 2017). "In contrast to our findings, Kay and colleagues have demonstrated that Tris DBA did not significantly inhibit the activation of STAT3 in primary chronic lymphocytic leukemia B-cells." (PMID 34771643, 2021). "In chronic lymphocytic leukaemia (CLL) cells, although both pS727 STAT3 and pY705 STAT3 activate the transcription of the same repertoire of genes, constitutively activated pS727 STAT3 not only activated anti-apoptotic genes, but also shows low-affinity binding to the caspase-3 promoter." (PMID 32331320, 2020). "It has been reported that excessive activation of the STAT3 pathway does not protect chronic lymphocytic leukemia cells from apoptosis." (PMID 28910419, 2017). "For example, it has been shown that non-catalytic functions of MMP-9 regulate STAT3 functions to drive survival in B-cell chronic lymphocytic leukemia (B-CLL) cells." (PMID 27158478, 2016).
myocardial ischemia (59 papers, 2004 to 2026). A disorder of cardiac function caused by insufficient blood flow to the muscle tissue of the heart. "During myocardial ischemia-reperfusion injuries, STAT3-deficient rats have larger cerebral infarct sizes and lower cardiac functions." (PMID 38022526, 2023). "In experimental animal models, STAT3-deficient mice were more sensitive to myocardial ischemia/reperfusion injury, the infarct area of the heart increased and the function and survival of the heart decreased." (PMID 35281886, 2022). "In order to determine how zinc deficiency acts on STAT3 activation in the myocardial ischemia/reperfusion injury, RNA-seq analysis was performed." (PMID 35069232, 2021). "STAT3 deficiency causes enhanced susceptibility to myocardial ischemia/reperfusion injury and infarction with increased cardiac apoptosis, increased infarct sizes, and reduced cardiac function and survival." (PMID 31269974, 2019). "However, how zinc deficiency acts on STAT3 activation in the myocardial ischemia/reperfusion injury remain unknown." (PMID 35069232, 2021). "This research demonstrates that the traditional Mongolian formula HL4 effectively mitigates myocardial ischemia/reperfusion injury by activating the pivotal pro-survival signaling pathway mediated by STAT3." (PMID 41268446, 2025). "Lan Wu also demonstrated that ROS, through the activation of the JAK2/STAT3 pathway, exhibits cardioprotective function in early cardiac ischemia–reperfusion injury." (PMID 39877839, 2025). "For example, Strychnine regulates oxidative stress and apoptosis by activating JAK2/STAT3 signaling pathway, thereby preventing myocardial ischemia–reperfusion injury." (PMID 39940217, 2025). "In the heart, ZIP2 protects against myocardial ischemia/reperfusion injury through improved mitochondrial function in a STAT3-dependent manner." (PMID 41583444, 2025). "Studies have shown that JUN is closely related to the JAK2/STAT3 signaling pathway and the PI3K-Akt signaling pathway, and it can effectively treat acute renal injury caused by myocardial ischemia." (PMID 39339421, 2024). "Baicalin alleviates myocardial ischemia-reperfusion injury and inflammation caused by retinal ischemia-reperfusion injury in rats by inhibiting the phosphorylation levels of the JAK2/STAT3 signaling pathway." (PMID 39555089, 2024). "The activation of STAT3 is crucial for reducing cardiac autophagy and inhibiting cardiac ischemia/reperfusion injury, as demonstrated by the inhibition of soluble receptor for advanced glycation end-products on cardiac ischemia/reperfusion injury." (PMID 38495094, 2024). "In summary, these data suggest that sympathetic denervation activates the STAT3 signal to protect the myocardial ischemia-reperfusion injury." (PMID 35433880, 2022). "The activation of STAT3 exacerbates cardiac dysfunction, myocardial ischemia/reperfusion injury, and cardiac fibroblast activation and cardiac fibrosis." (PMID 34923910, 2022). "Activation of STAT3 has been shown to reduce myocardial cell apoptosis during myocardial ischemia injury." (PMID 36225565, 2022). "Cardiomyocyte-specific deletions of either STAT3 or STAT5 in mice subjected to models of myocardial ischemia/reperfusion emphasized their requirement for cardiomyocyte survival via upregulation of anti-apoptotic and anti-oxidant proteins." (PMID 35008777, 2021). "STAT3 counteracts oxidative stress in acute myocardial ischemia, exerting cardioprotective activity via preservation of mitochondrial integrity and modulation of transcriptional responses." (PMID 30312306, 2018). "JAK2/STAT3 activation can attenuate mitochondrial oxidative damage induced by myocardial ischemia/reperfusion injury and maintain mitochondrial function." (PMID 29441065, 2018). "Accordingly, upon induction of cardiac ischemia, STAT3 protects complex I-dependent respiration from injury, decreasing cytochrome c release and ROS production." (PMID 26106584, 2015).
myocardial ischemia (continued). "Like STAT5, STAT3 was also shown to be protective against cardiac ischemia/reperfusion injury through a JAK2/STAT3-dependent mechanism involving up-regulation of anti-apoptotic Bcl2 and down-regulation of pro-apoptotic Bax." (PMID 15296508, 2004). "In summary, this study systematically elucidates HL4’s cardioprotective mechanism via the STAT3/HIF-1α axis, providing a robust scientific foundation for its clinical application and laying groundwork for developing STAT3-targeted therapies for myocardial ischemia-reperfusion injury." (PMID 41268446, 2025). "In addition, it can also promote the secretion of IL-10 and activate the JAK2/STAT3 signaling pathway, showing pharmacological effects in alleviating myocardial ischemia/reperfusion injury." (PMID 39942654, 2025). "Finally, a protein-protein interaction network was constructed to validate the involvement of Stat3, Rela, and Ubb as hub genes in angiogenesis during the progression of myocardial ischemia-reperfusion injury." (PMID 38935597, 2024). "After myocardial ischemia, STAT3 activation promotes cardiomyocyte survival." (PMID 38022526, 2023). "Interestingly, DPP-4 inhibition improves cardiac function and reduces myocardial ischemia through SDF-1a/CXCR4-mediated STAT3 signaling and exerts an antiapoptotic effect on HUVEC under hypoxic conditions." (PMID 35615279, 2022). "Taken together, NIL10 may act as an anti-inflammatory effector through the IL-10/STAT3 signaling pathway in myocardial ischemia/reperfusion." (PMID 36297479, 2022). "Similarly, other researchers demonstrated that JAK2/STAT3 signaling was effectively up-regulated during myocardial ischemia and aggravated injury." (PMID 35655588, 2022). "Moreover, previous studies have reported that the signal transducer and activator of transcription (STAT3) pathway plays significant regulatory roles in maintaining mitochondrial function in myocardial ischemia." (PMID 31816825, 2019). "Examining a pathophysiological role of SgII in the initial phase of post-infarction HF, the SgII fragment secretoneurin reduced myocardial ischemia-reperfusion injury and cardiomyocyte apoptosis by 30% and rapidly increased cardiomyocyte Erk1/2 and Stat3 phosphorylation." (PMID 22655045, 2012). "In the case of the role of JAK/STAT3 pathway in neovascularization under MI, STAT3 cardiac specific KO mice exhibited reduced myocardial capillary density and more susceptibility to myocardial ischemia/reperfusion injury, even though no variations in VEGF expression was observed." (PMID 37569674, 2023). "In conclusion, similar to its transcriptionally active counterpart, mitochondrial STAT3 is potentially able to regulate cellular metabolism to warrant cell survival to apoptotic stimuli upon different kinds of stress such as, for example, cardiac ischemia or oncogenic transformation." (PMID 26106584, 2015). "In myocardial ischemia and infarction models, the protective effects of GSH-inducing substances were abolished by AG490 treatment, suggesting a role for JAK2/STAT3 in modulating GSH levels." (PMID 40802001, 2025). "Mechanistically, L‐theanine has been shown to mitigate myocardial ischemia–reperfusion injury by suppressing apoptosis and oxidative stress via JAK2/STAT3 signaling." (PMID 41230384, 2025). "Myocardial ischemia, hypoxia, and reperfusion are considered as stressors that stimulate the production of related cytokines, thus activating the JAK2/STAT3 signaling pathway and providing cardioprotection." (PMID 35263202, 2022). "While spontaneous STAT3 activation has been shown to occur after myocardial ischemia and was further increased by reperfusion, it failed to reduce the infarct size." (PMID 29872405, 2018). "In an animal model of myocardial ischemia/reperfusion, DEX alleviated myocardial mitochondrial apoptosis through a pathway involving the lncRNA HCP5/miR-29a/MCL1 axis and activation of Janus kinase 2/signal transducer and activator of transcription 3 signaling." (PMID 39881865, 2024).
myocardial ischemia (continued). "We found that GRS at the concentration of 10 μg/mL could inhibit the phosphorylation of JAK2 and STAT3 under H/R conditions, suggesting that GRS might play a role in protecting myocardial ischemia injury through the inactivation of JAK2-STAT3 signaling pathway." (PMID 28197101, 2017).
diabetic nephropathy (57 papers, 2005 to 2026). "A recent study on a T2DM mouse model showed that G. uralensis root effectively suppressed high-glucose-induced TGF-β1 production by regulating Smad/Stat3-mediated mechanisms, potentially attenuating fibrosis-associated diabetic nephropathy." (PMID 39337550, 2024). "The majority of the STAT3 activation was reported to be associated with renal diseases in humans, including diabetic nephropathy and acute renal injury, as well as chronic renal disorders." (PMID 39734345, 2024). "STAT3 transcriptional activation has been implicated in the pathogenesis of diabetic kidney disease, Alport syndrome, lupus nephritis, nephrotoxic nephritis, and polycystic kidney disease." (PMID 33755599, 2021). "Isoquercitrin, a natural small‐molecule inhibitor of STAT3, may have beneficial effects on diabetic nephropathy; however, the underlying mechanism remains unclear." (PMID 40184310, 2025). "In a mouse model of diabetic kidney disease (the most common form of human chronic kidney disease), mice that are heterozygous for a STAT3 loss of function mutation have reduced interstitial fibrosis and inflammation, and improved renal function compared to diabetic mice with wild-type STAT3." (PMID 26678048, 2015). "Another study in mouse with diabetic nephropathy demonstrated that the activation of JAK2/STAT3 signaling pathway in the kidney residual macrophages induced the release of proinflammatory factors and ROS, worsening kidney damage." (PMID 40700116, 2025). "In diabetic nephropathy, miR-223 is downregulated, and miR-223-3p has been shown to mediate the diabetic kidney disease progression by targeting IL6ST/STAT3 pathway, indicating protective mechanisms against diabetic kidney disease." (PMID 41295241, 2025). "Andrographolide targets diabetic nephropathy drivers (inflammation, oxidative stress, apoptosis) via STAT3/PI3K/Akt regulation." (PMID 41008970, 2025). "Previous research has shown that MLT exerts an ameliorative effect on diabetic nephropathy, as it can reduce renal cell apoptosis by regulating STAT3 phosphorylation." (PMID 41515187, 2025). "Research has shown that dulaglutide plays a reno-protective role in diabetic nephropathy by regulating p-STAT3 signaling, inhibiting inflammation and ferroptosis, and improving renal fibrosis." (PMID 40298655, 2025). "Isoquercitrin significantly mitigated renal inflammation and fibrosis by inhibiting STAT3 activity in mice with diabetic nephropathy." (PMID 40184310, 2025). "At the convergence point of multiple cytokine signals, signal transducer and activator of transcription 3 (STAT3) is a highly promising therapeutic target for diabetic nephropathy." (PMID 40184310, 2025). "The same group also reported that Na2S4 prevents diabetic nephropathy by attenuating apoptosis via NF-κB and STAT3 inactivation." (PMID 38256961, 2024). "The SPL substrate S1P and the pro-inflammatory transcription factor STAT3 stimulate mutually co-activating pathways that can drive inflammatory processes, including diabetic kidney disease." (PMID 37958544, 2023). "Recent findings show that signal transducer and activator of transcription 3 (STAT3) is one of the vital signaling pathways in the development of diabetic nephropathy." (PMID 34233296, 2021). "It has been reported that high glucose directly induced STAT3 phosphorylation of renal tubular epithelial cells and pharmacological inhibition of STAT3 attenuated the progression of diabetic nephropathy." (PMID 34193173, 2021). "We firstly explored the endogenous expression of MBNL1, miR-130a-3p, and STAT3 in diabetic nephropathy and their relation with the senescence of renal tubular epithelial cells." (PMID 32104542, 2020). "Our results suggest that metformin reduces the senescence of renal tubular epithelial cells in diabetic nephropathy via the MBNL1/miR-130a-3p/STAT3 pathway, which provided new ideas for the therapy of this disease." (PMID 32104542, 2020).